RNU6-675P (RNA, U6 small nuclear 675, pseudogene)
Gene: Small nuclear RNA gene on chromosome 2 (126,702,839 to 126,702,942, reverse strand). Ensembl gene ENSG00000206963.
Homologues: Orthologues: chimpanzee U6 (100% identical), macaque U6 (95% identical), pig U6 (85% identical). Paralogues in human: RNU6-19P (91% identical), RNU6-761P (91% identical), RNU6-1060P (90% identical), RNU6-12P (90% identical), RNU6-13P (90% identical), RNU6-166P (90% identical), RNU6-25P (90% identical), RNU6-26P (90% identical), RNU6-31P (90% identical), RNU6-32P (90% identical), RNU6-35P (90% identical), RNU6-41P (90% identical), and 1284 more.